DCLK2 (doublecortin like kinase 2)
Description:
Protein kinase with a significantly reduced C(a2+)/CAM affinity and dependence compared to other members of the CaMK family. May play a role in the down-regulation of CRE-dependent gene activation probably by phosphorylation of the CREB coactivator CRTC2/TORC2 and the resulting retention of TORC2 in the cytoplasm (By similarity).
Synonyms: CL2; CLICK-II; CLICK2; DCAMKL2; DCDC3B; DCK2; MGC45428; DCDC3; CLIK2
Tractability: Small molecule: a high-quality ligand is known; it belongs to a druggable protein family. PROTAC: ubiquitination databases record sites on it; its protein half-life has been measured; a small molecule that binds it is known.
Target class: CAMK protein kinase DCAMK1 family; Kinase; CAMK protein kinase group; Enzyme; Protein Kinase
Chemical probes: DCLK1-IN-1 (high quality)
Gene: Protein-coding gene on chromosome 4 (150,078,176 to 150,257,454, forward strand). Ensembl gene ENSG00000170390.
Subcellular location: Cytoplasm, cytoskeleton
Gene Ontology:
Molecular function: protein binding; protein serine/threonine kinase activity; ATP binding; protein kinase activity; protein serine kinase activity
Biological process: microtubule cytoskeleton organization; central nervous system development; intracellular signal transduction
Cellular component: cytoplasm; cytoskeleton
Genetic constraint (gnomAD): Loss-of-function variants: 26 observed, 68.7 expected, observed/expected ratio (o/e) 0.38, 90% interval 0.28 to 0.52. The upper end of that interval is the gene's LOEUF score, 0.52, which puts it in group 2 of 6, group 1 being the genes least tolerant of losing a copy. Missense variants: 815 observed, 907.47 expected, observed/expected ratio (o/e) 0.9, 90% interval 0.85 to 0.95. Synonymous variants: 386 observed, 349.58 expected, observed/expected ratio (o/e) 1.1, 90% interval 1.01 to 1.2.
Homologues: Orthologues: chimpanzee DCLK2 (99% identical), macaque DCLK2 (99% identical), rabbit DCLK2 (95% identical), mouse Dclk2 (93% identical), guinea pig DCLK2 (93% identical), dog DCLK2 (93% identical), rat Dclk2 (93% identical), pig DCLK2 (92% identical), tropical clawed frog dclk2 (77% identical). Paralogues in human: DCLK1 (66% identical), DCLK3 (30% identical), MYLK3 (20% identical), CAMK2G (18% identical), CAMKK2 (18% identical), CAMK1 (18% identical), CAMK1D (18% identical), CAMK2B (18% identical), CAMK2D (18% identical), PNCK (18% identical), CAMK2A (17% identical), PSKH1 (17% identical), and 10 more.
Diseases named in the same sentence as DCLK2 in open-access papers:
DCLK2 is named in the same sentence as 14 diseases in open-access papers, as found by Europe PMC text mining. Sharing a sentence is not in itself a finding about the gene and the disease. The quoted sentences say what the papers report.
Alcohol Use Disorder (1 paper, 2023). "Furthermore, DCLK2, 1 of the miR-3937 putative target genes, was previously associated in a trans-ethnic genome-wide association analysis of Alcohol Use Disorder Identification Test (AUDIT)-Consumption (rs4423856, P = 1.48 × 10−8)." (PMID 36130258, 2023).
attention deficit-hyperactivity disorder (1 paper, 2012). A disorder characterized by a marked pattern of inattention and/or hyperactivity-impulsivity that is inconsistent with developmental level and clearly interferes with functioning in at least two settings (e.g. at home and at school). "Rare copy number variations of Doublecortin like kinase-2, DCLK2, were detected in a study investigating attention deficit hyperactivity disorder (ADHD)." (PMID 24705084, 2012).
colorectal cancer (1 paper, 2022). A primary or metastatic malignant neoplasm that affects the colon or rectum. "DCLK2 was identified as having synthetic lethal interaction with mutant Ras in colorectal cancer, suggesting that it may be an enticing target for cancers drive by the Ras oncogene." (PMID 36686695, 2022).
diabetic cardiomyopathy (1 paper, 2025). Diabetic cardiomyopathy is a disorder of the heart muscle in people with diabetes. "Changes in AS of ATP5C1, DCLK2, and MAP3K4 rewire interactions with a “Hypertrophic cardiomyopathy” pathway, and of CACNA1C, TPM3, and ITGB1 rewire interactions with the “Diabetic cardiomyopathy” pathway." (PMID 40337913, 2025).
helminth infection (1 paper, 2021). "Similar to the tissue sampled post-helminth infection, probes to IL17RB, TAS2R16 and DCLK-2 co-localized with POU2F3 probe, but in a lower number of cells, as expected from our IHC data." (PMID 34880874, 2021).
cancer (2 papers, 2021 to 2022). A tumor composed of atypical neoplastic, often pleomorphic cells that invade other tissues. "It will be of interest to further explore the role of DCLK2 in endothelial cell biology and cancer." (PMID 36686695, 2022).
neurodevelopmental disorder (1 paper, 2021). A behavioral and cognitive disorder with onset during the developmental period that involves impaired or aberrant development of intellectual, motor, or social functions. "DCX-inactivating mutations cause severe structural brain abnormalities, whereas the case for DCLK1 and DCLK2 as disease genes for neurodevelopmental disorders is currently circumstantial." (PMID 33199366, 2021).
DCLK2 also shares sentences with these, for which no sentence is quoted: gastric cancer (1 paper); genetic disorder (1); glioma (1); hypertrophic cardiomyopathy (1); mucolipidosis type IV (1); renal clear cell carcinoma (1); tumor (1).